PGR (progesterone receptor)
Diseases named in the same sentence as PGR in open-access papers (continued):
Sharing a sentence is not in itself a finding about the gene and the disease.
triple-negative breast carcinoma (continued). "Triple-negative breast cancer is a subtype of breast cancer where cancer cells lack the human epidermal growth factor receptor 2 (HER2), estrogen receptor (ER), and progesterone receptor (PR)." (PMID 38186581, 2023). "Similar transcriptomic analyses were performed by Xu and colleagues in a study of 360 Chinese patients with triple-negative breast cancer (TNBC), an aggressive breast cancer subtype that expresses low levels of ER, progesterone receptor (PR), and her2/neu." (PMID 37887304, 2023). "Triple-negative breast cancer (TNBC) is a term that has been applied to cancers that lack expression of the estrogen receptor (ER), progesterone receptor (PR) and human epidermal growth factor receptor 2 (HER2)." (PMID 37241035, 2023). "Triple-negative breast cancer (TNBC) lacks estrogen receptor, progesterone receptor, and human epidermal growth factor receptor 2 expressions, making targeted therapies ineffective." (PMID 37189800, 2023). "Triple-negative breast cancer (TNBC) is a subtype of breast cancer that lacks expression of Estrogen Receptor (ER), Progesterone Receptor (PR), and Human Epidermal growth factor Receptor 2 (HER-2)." (PMID 37609372, 2023). "This heterogeneous disease is currently broadly classified as estrogen receptor (ER), progesterone receptor (PR) positive luminal tumors, human epidermal growth factor receptor 2 (HER2) amplified tumors and triple-negative breast cancers (TNBC)." (PMID 38765717, 2023). "Triple negative breast cancer (TNBC) is a specific type of breast cancer that lacks estrogen receptor (ER), progesterone receptor (PR), and human epidermal growth factor receptor-2 (HER2), and accounts for approximately 15% of all breast cancer cases." (PMID 38047286, 2023). "Triple-negative breast cancer (TNBC) is a type of breast tumor with a poor prognosis because it lacks or expresses low levels of estrogen receptor (ER), progesterone receptor (PR), and human epidermal growth factor receptor 2 (HER-2)." (PMID 37773118, 2023). "Triple-negative breast cancer (TNBC) is characterized by estrogen receptor-negativity (ER-), progesterone receptor-negativity (PR-) and human epidermal growth factor receptor 2-negativity (HER2-negative)." (PMID 35031634, 2022). "Triple-negative breast cancer (TNBC) represents one specific type of breast cancer that lacks the expression of estrogen receptor (ER), progesterone receptor (PR), and human epidermal growth factor receptor-2 (HER2)." (PMID 36405394, 2022). "Triple-negative breast cancer (TNBC) lacks an estrogen receptor (ER), progesterone receptor (PR), and HER2 receptor." (PMID 36011019, 2022). "Triple-negative breast cancer (TNBC) is the most malignant and aggressive molecular subtype of breast cancer that lacks the expression of the estrogen receptor (ER), progesterone receptor (PR), and human epidermal growth factor receptor 2 (HER2)." (PMID 36685836, 2022). "The classic subtyping, based on estrogen receptor (ER), progesterone receptor (PR), and human epidermal growth factor receptor 2 (HER2) status, includes ER+HER2−, HER2+, and triple-negative breast cancer (TNBC)." (PMID 35151316, 2022). "Triple-negative breast cancer (TNBC) is diagnosed based on the negativity of all three receptors that are found in other breast cancer types: estrogen receptor (ER), progesterone receptor (PR), and human epidermal growth factor (HER-2)." (PMID 35774120, 2022). "Triple negative breast cancer (TNBC) is an aggressive subtype of breast cancer that lacks the expression of human epidermal growth factor receptor 2 (HER2), progesterone receptor (PR), and estrogen receptor (ER)." (PMID 35745832, 2022). "BRCA has four categories, including estrogen receptor (ER+), progesterone receptor (PR+), human epidermal receptor 2 (HER2+) and triple negative breast cancer (TNBC), which correlate to the expression of hormonal receptors." (PMID 36551227, 2022).
triple-negative breast carcinoma (continued). "Immunostaining showed the estrogen receptor (ER)/progesterone receptor (PR) subtype in 43 patients (53.1%), HER2 subtype in 18 patients (22.2%), and triple-negative breast cancer (TN) subtype in 20 patients (24.7%)." (PMID 36362023, 2022). "Triple-negative breast cancer (TNBC) cells that lack the expression of estrogen receptor (ER), progesterone receptor (PR), and human epidermal growth factor receptor 2 (HER2), often exhibit the molecular and functional traits of cancer stem cells." (PMID 36207293, 2022). "Triple-negative breast cancer (TNBC) is defined as estrogen receptor (ER), progesterone receptor (PR), and human epidermal growth factor receptor 2 (HER-2)." (PMID 35664559, 2022). "Triple-negative breast cancer (TNBC), which lacks the expression of the estrogen receptor (ER), progesterone receptor (PR), and human epidermal growth factor receptor 2 (HER2), accounts for 10–15% of breast cancers." (PMID 35413945, 2022). "Triple-negative breast cancer (TNBC) accounts for 15–20% of breast cancers that lack estrogen receptor (ER) and progesterone receptor (PR) expression and human epidermal growth factor 2 (HER2) amplification." (PMID 34621789, 2021). "Triple-negative breast cancer (TNBC) presents as a subtype express estrogen receptor (ER), progesterone receptor (PR) and human epidermal growth factor receptor 2 (Her-2) insufficiently." (PMID 33747900, 2021). "Triple-negative breast cancer (TNBC) represents a heterogeneous group of breast cancers that lack estrogen receptor (ER), progesterone receptor (PR), and human epidermal factor 2 (HER2) amplifications." (PMID 33915941, 2021). "Triple negative breast cancer (TNBC) poses a serious clinical challenge as it is an aggressive form of the disease that lacks estrogen receptor, progesterone receptor, and ERBB2 (formerly HER2) gene amplification, which limits the treatment options." (PMID 34649623, 2021). "The subtypes are as follows: Luminal A (ER+ and/or PgR+, HER2-, Ki-67 < 14%), Luminal B (ER+ and/or PgR+, HER2-, Ki-67 high or ER+ and/or PgR+, HER2+, Ki-67 any), HER2-enriched (ER-, PgR-, HER2+) and triple negative breast carcinoma (TNBC) (ER-, PgR-, HER2-)." (PMID 34440036, 2021). "Triple-negative breast cancer (TNBC), which lacks estrogen receptor (ER), progesterone receptor (PR) and human epidermal growth factor receptor 2 (HER2) expression, is associated with a lower disease-free and overall survival compared to the other subtypes." (PMID 34202498, 2021). "Triple-negative breast cancer (TNBC) is characterized by estrogen receptor-, progesterone receptor-, and HER2-negative, which is extremely aggressive with a high risk of metastasis." (PMID 34795289, 2021). "According to the Her2, ER, and PgR expressions, we divided patients into HER2-enriched, triple-negative breast cancer (TNBC) and other subtypes (n = 8, 28, 55, respectively)." (PMID 35154262, 2021). "By contrast, triple-negative breast cancer (TNBC) lacks these three receptors (estrogen receptor (ER), progesterone receptor (PR), and HER2) and, thus, is a diagnosis of exclusion showing the basal subtype in molecular profiling." (PMID 34681231, 2021). "The subtypes are: I) luminal A (ER+, PgR+, HER2-), II) luminal B (ER+, PgR+, HER2-/+), III) HER2-overexpressing (ER-, PgR-,HER2+), IV) triple negative breast cancer (TNBC; ER-, PgR-, HER2-) and, V) normal-like subtype." (PMID 32287294, 2020). "Triple-negative breast cancer (TNBC) is a subtype that lacks the expression of estrogen receptor (ER), progesterone receptor (PgR), and human epidermal growth factor receptor 2 (HER2)." (PMID 32850353, 2020). "Triple negative breast cancer (TNBC), which is more common in African Americans, is a cancer in which the expression of estrogen receptor (ER), progesterone receptor (PR), and human epidermal growth factor 2 receptor (HER2) is missing." (PMID 33425763, 2020).
triple-negative breast carcinoma (continued). "Triple-negative breast cancer (TNBC), which lacks the expression of the estrogen receptor (ER), progesterone receptor (PR), and excess amplification of human epidermal growth factor receptor 2 (HER2), is the most aggressive subtype of breast cancer." (PMID 33154433, 2020). "MpBC is typically a triple-negative breast cancer (TNBC), meaning the tumor lacks the expression of estrogen receptor (ER), progesterone receptor (PR), and human epidermal growth factor 2 receptor (HER2)." (PMID 33148288, 2020). "Triple-negative breast cancer (TNBC) accounts for 15–20% of all diagnosed BCs and is a tumor type characterized by lack of expression of three markers: estrogen receptor (ER), progesterone receptor (PR), and human epidermal growth factor receptor 2 (HER2)." (PMID 30884823, 2019). "Triple-negative breast cancer (TNBC) is highly proliferative and metastatic, and because it lacks three major molecular targets for chemotherapy (estrogen receptor, progesterone receptor, and human epidermal receptor 2), it is extremely refractory." (PMID 31261818, 2019). "Triple negative breast cancer (TNBC) tumors lack expression of estrogen receptor (ER), progesterone receptor (PR), and human epithelial growth factor receptor 2 (HER2)." (PMID 31821346, 2019). "Triple negative breast cancer (TNBC) lacks the expression of ER, progesterone receptor (PR) and HER-2." (PMID 31506466, 2019). "Triple-negative breast cancer (TNBC) lacks expression of estrogen receptor (ER) and progesterone receptor (PR) and exhibits overexpression of human epidermal growth factor receptor 2 (HER2)." (PMID 30999598, 2019). "Triple-negative breast cancer (TNBC) cells, which lack estrogen receptor (ER), progesterone receptor (PR) and human epidermal growth factor receptor 2 (HER2), grow faster than most other breast cancer cell types." (PMID 31804974, 2019). "It is a heterogeneous disease, mainly categorized based on hormone receptor status; estrogen receptor (ER), progesterone receptor (PR) positive, human epidermal growth factor receptor 2 (HER2) positive, and triple negative breast cancer (TNBC)." (PMID 31505846, 2019). "12–15% of all tumors lack immunohistochemical expression of estrogen receptor (ER), progesterone receptor (PR) and human epidermal growth factor receptor 2 (HER2) and are therefore termed triple-negative breast cancers (TNBC)." (PMID 30257646, 2018). "Triple-negative breast cancer (TNBC) is a breast cancer subtype that lacks the expression of hormone receptors (estrogen receptor (ER) and progesterone receptor (PR)) and human epidermal growth factor receptor 2 (HER2)." (PMID 30594216, 2018). "Triple-negative breast cancer (TNBC) is a subtype of breast cancer that lacks the expression of the estrogen receptor (ER), progesterone receptor (PR) and epidermal growth factor receptor-2 (Her2)." (PMID 30388728, 2018). "Triple-negative breast cancer (TNBC), which lacks expression of estrogen receptor (ER), progesterone receptor (PR) and HER-2, is believed to have a relatively aggressive tumor biology." (PMID 28915596, 2017). "Triple-negative breast cancer (TNBC) lacks the expression of estrogen receptor α, progesterone receptor and human epidermal growth factor receptor 2 (HER2)." (PMID 28422142, 2017). "These aggressive tumors lack expression of estrogen receptor (ER), progesterone receptor (PR), and human epidermal growth factor receptor 2 (HER2) are thus referred to as triple-negative breast cancer (TNBC)." (PMID 28423498, 2017). "In particular, triple-negative breast cancer (TNBC), which lacks the expression of estrogen receptor (ER), progesterone receptor (PR), and human epidermal growth factor receptor 2 (HER2), encompasses a heterogeneous collection of tumors." (PMID 28106823, 2017). "Breast cancers devoid of Estrogen Receptor (ER-), Progesterone Receptor (PR-), and HER2 expression (HER2-) are termed Triple-Negative Breast Cancers." (PMID 28423644, 2017).
triple-negative breast carcinoma (continued). "Triple negative breast cancer (TNBC), characterized by the lack expression of estrogen receptor (ER), progesterone receptor (PR), and human epidermal growth factor receptor 2 (HER2), accounts for approximately 15 to 20% of all breast cancers." (PMID 29190901, 2017). "Triple-negative breast cancer (TNBC) is a subclass of breast tumors that lack estrogen receptor (ER) and progesterone receptor (PgR) expression, as determined by immunohistochemistry (IHC)." (PMID 27977696, 2016). "Summary of treatment for (A) ER- and PgR-positive tumors, (B) luminal A, luminal B, HER2-positive, triple-negative breast cancers, and (C) HER2-positive and HER2-negative tumors." (PMID 27336872, 2016). "Triple-negative breast cancer (TNBC) is characterized by the limited expression of the human epidermal growth factor receptor 2 (HER2), estrogen receptor (ER), and progesterone receptor (PR) and accounts for approximately 15 % of invasive breast cancers." (PMID 27439908, 2016). "Triple-negative breast cancer (TNBC), defined as a tumor that lacks expression of the oestrogen receptor (ER), the progesterone receptor (PR), and human epidermal growth factor receptor 2 (HER2), accounts for 15–20% of all breast cancer cases." (PMID 27203673, 2016). "Basal-like breast cancer usually lacks the expression of estrogen receptor (ER), progesterone receptor (PR) and Human Epidermal Growth Factor Receptor 2 (HER-2), which is generally defined as triple negative breast cancer (TNBC)." (PMID 25734578, 2015). "Triple-negative breast cancer (TNBC) is an invasive carcinoma, of the breast, that lacks expression of the estrogen receptor (ER), progesterone receptor (PR) and human epidermal growth factor receptor 2 (HER2)." (PMID 25544759, 2015). "Basal-like breast cancer (BLBC) is less likely to express estrogen receptor (ER), progesterone receptor (PR) and HER2, which are also characteristics of triple-negative breast cancer (TNBC)." (PMID 25848863, 2015). "Triple-negative breast cancer (TNBC) is an invasive type of breast carcinoma that lacks expression of the estrogen receptor (ER) and progesterone receptor (PR) as well as human epidermal growth factor receptor 2 (HER2) amplification." (PMID 25970785, 2015). "A separate set of subtyping criteria relies on the expression of important therapeutic markers: estrogen receptor (ER), progesterone receptor (PR), and HER-2, from which the term triple negative breast cancer (TNBC) is derived." (PMID 24884785, 2014). "Patients with triple-negative breast cancers (TNBC; estrogen receptor-, progesterone receptor-, and HER2-negative) typically have a poor prognosis; thus, there is an increasing need for new therapeutic approaches that target TNBC." (PMID 24970818, 2014). "In this study, we also reported that Toca-1 expression levels are high in triple-negative breast cancer (TNBC) cell lines, which lack expression of estrogen receptor (ER)/progesterone receptor (PR)/human epidermal growth factor receptor 2 (HER2) receptors." (PMID 25547174, 2014). "Triple-negative breast cancer (TNBC), which lacks expression of estrogen receptor (ER), progesterone receptor (PR), and HER-2, is characterized by poor prognosis and extreme heterogeneity." (PMID 24945253, 2014). "The basal-like breast cancer subtype, which commonly lacks expression of the estrogen receptor (ER), progesterone receptor (PR), and human epidermal growth factor receptor 2 (HER2), is widely perceived as being synonymous with triple-negative breast cancer." (PMID 23620774, 2013). "We used three cell lines representing triple-negative breast cancers, BT-549 and MDA-MB-231 (claudin-low), and MDA-MB-468 (basal-like), along with estrogen and progesterone receptor positive MCF-7 cells (luminal)." (PMID 23761858, 2013). "Unfortunately triple-negative breast cancer (TNBC) is a biological entity that lacks estrogen receptors (ER), progesterone receptors (PGR), and human epidermal growth factor receptor 2 (HER2)." (PMID 23342258, 2012).
triple-negative breast carcinoma (continued). "Triple negative breast cancer (TNBC) are tumors that lack expression of estrogen receptor α (ERα), progesterone receptor (PR), and amplification/overexpression of human epidermal growth factor receptor 2 (HER2/neu)." (PMID 22457730, 2012). "Triple-negative breast cancer (TNBC) is defined histologically as invasive carcinoma of the breast that lacks staining for estrogen receptor (ER), progesterone receptor (PgR), and the human epidermal growth factor receptor-2 (HER2)." (PMID 22713668, 2012). "Clinically, breast tumours that lack the expression of Oestrogen Receptor, Progesterone Receptor and Human Epidermal growth factor Receptor 2 (HER2) are identified as presenting a "triple-negative" phenotype or as triple-negative breast cancers." (PMID 21762477, 2011). "The mean metabolite profiles demonstrated that triple negative breast cancer tissue had high GPC and low PCho concentrations, whereas tissue from ER+/PgR+ patients had low GPC and high PCho." (PMID 20716336, 2010). "Triple-negative breast cancers (TNBCs) are known to be negative for estrogen receptor, progesterone receptor or HER2 protein expression." (PMID 41229499, 2025). "Since triple-negative breast cancer (TNBC) lacks an effective treatment target, that is, classic estrogen receptor (ERα), progesterone receptor (PgR), or human epidermal growth factor receptor-2 (HER2), chemotherapy is the most established pharmacotherapy for patients with TNBC." (PMID 41373615, 2025). "Breast cancer provides an illustrative case: triple-negative breast cancer (TNBC), which lacks estrogen receptor (ER), progesterone receptor (PR), and human epidermal growth factor receptor 2 (HER2), often shows increased reliance on amino acids, including BCAAs." (PMID 41502503, 2025). "Additionally, BC mortality varies across BC subtypes, which include luminal A and B (estrogen receptor (ER) and progesterone receptor (PR) positive), HER2-positive, basal-like, and triple-negative breast cancer (TNBC)." (PMID 40227747, 2025). "Among its subtypes, triple-negative breast cancer (TNBC), which lacks estrogen receptor (ER), progesterone receptor (PR), and human epidermal growth factor receptor 2 (HER2) expression, is highly heterogeneous with early metastasis and a poor prognosis, making it the most challenging subtype." (PMID 40723842, 2025). "Similar to human breast cancer, different subtypes, such as estrogen receptor (ER)/progesterone receptor (PR)-positive, human epidermal growth factor receptor 2 (HER2)-positive, and triple-negative breast cancer (TNBC), have been observed in canine breast cancers." (PMID 40507124, 2025). "Triple negative breast cancer (TNBC) is defined by the lack of estrogen (ER) or progesterone receptor (PR) expression and no amplification/overexpression of the human epidermal growth factor receptor 2 (HER2) gene." (PMID 40328734, 2025). "Triple-negative breast cancer (TNBC) is a highly aggressive subtype of breast cancer that lacks expression of estrogen receptor (ER), progesterone receptor (PR), and human epidermal growth factor receptor 2 (HER2), and is thus associated with higher invasiveness, metastasis, and poor prognosis." (PMID 40906079, 2025). "MDA-MB-231 represents a triple-negative breast cancer cell line, characterized by the absence of estrogen receptor (ER), progesterone receptor (PR), and HER2." (PMID 41150178, 2025). "Triple-negative breast cancer (TNBC) is molecularly defined by the absence of expression of three prognostically significant receptors: the progesterone receptor (PR), estrogen receptor (ER), and human epidermal growth factor receptor 2 (HER2)." (PMID 40422572, 2025). "Categorization into four principal subtypes (luminal A, luminal B, human epidermal growth factor receptor 2-positive [HER2+], and triple-negative breast cancer [TNBC]) is facilitated by disparities in estrogen receptor (ER), progesterone receptor (PgR), HER2, and the Ki67 proliferation index." (PMID 39267843, 2024).